MTOR (mechanistic target of rapamycin kinase)
Diseases named in the same sentence as MTOR in open-access papers (continued):
Sharing a sentence is not in itself a finding about the gene and the disease.
infection (continued). "RNA sequencing and qPCR analysis of IAV-infected A549 cells and NP transfected cells revealed that miR-101 downregulates mTOR transcripts at later stages of infection." (PMID 32326380, 2020). "The extracellular signal-regulated kinase/mitogen-activated protein kinase (ERK/MAPK) and phosphoinositol 3-kinase/serine-threonine kinase/mammalian target of rapamycin (PI3K/AKT/mTOR) signaling networks play important roles in infection with this virus." (PMID 33022924, 2020). "An analysis of mTOR activity in virus-specific CD4 T cells revealed a similar dynamic pattern: mTOR signaling reaches a peak at day 2 postinfection and drops to a baseline level at day 8 after infection." (PMID 32999031, 2020). "The energetic demands of these infections can affect the hosts’ immune capacity by suppressing activity of immunometabolic proteins like mTOR." (PMID 32674261, 2020). "The activation was more prominent at 24hpi suggesting that SARS-CoV-2 activates Akt-mTOR signaling during the initial phase of infection." (PMID 32691695, 2020). "Consistently, the p-mTOR was down-regulated to a lower level in WT PCV2 infection group compared to that in the PCV2ΔORF5 infection group." (PMID 32184774, 2020). "The PI3K/MTOR inhibitor (dactolisib) and PI3K/MTOR/BRD4 inhibitor (SF2523, JQ1) restrain HIV replication through degradative autophagy without altering the initial susceptibility of macrophages to infection." (PMID 32265919, 2020). "Inhibiting this pathway with rapamycin (mTOR) or wortmannin (Akt) during infection with Δku80 conidia impaired the ability of macrophages to reprogram their metabolism, leading to lower levels of secreted lactate." (PMID 32385235, 2020). "HIF-1α and the mammalian target of the rapamycin (mTOR) pathway are critical for driving an immunometabolic signaling toward glycolysis during infection." (PMID 32922385, 2020). "HIV-1 protein Env has been proposed to downregulate autophagy by activating mTOR and reducing lysosomal enzyme activity in DCs, thereby inhibiting antigen presentation and enhancing the transfer of infection into CD4+ T cells." (PMID 32265919, 2020). "However, a considerable decrease was observed in p-mTOR and total mTOR protein levels, whereas p-4EBP1 levels increased moderately at 48 hpi, indicating that the former is regulating the levels of later causing the infected cells to decrease protein synthesis as the duration of infection increases." (PMID 32326380, 2020). "Accordingly, our initial findings support the notion that rickettsiae likely exploit activation of mTOR during infection to interfere with the autophagic response of ECs." (PMID 33003310, 2020). "Infections can be potent modifiers of energy metabolism with the ability to regulate mTOR signalling." (PMID 32130224, 2020). "The activation of the mTOR pathway during infection was confirmed by the enhanced phosphorylation of the p70S6 kinase, a downstream target of the mTORC1 complex." (PMID 32385235, 2020). "In line with the impaired phosphorylation of the mTOR target p70S6 kinase, mTOR expression was also decreased during infection with ΔpksP conidia, a defect that was rescued by the CaM antagonist W7." (PMID 32385235, 2020). "A significant and progressive increase in the levels of p-mTOR, total mTOR and NP levels were observed upon infecting A549 cells with X-31 virus at increasing time of infection and MOI." (PMID 32326380, 2020). "Contrary to the trend of LC3-II and Beclin1, the p-mTOR level increased with the extension of infection time." (PMID 32676067, 2020). "During the acute phase of the infection, the mTOR pathway orchestrated a shift from OXPHOS to glycolysis in PBMCs stimulated with either C. albicans or LPS (E. coli)." (PMID 33336295, 2020). "Patients with mammalian target of rapamycin (mTOR) inhibitors showed a significantly higher infection rate than those receiving CNIs." (PMID 32947774, 2020).
infection (continued). "In the early stages of infection mTOR is activated and autophagy is decreased, while later in infection autophagy is activated through mTOR-independent mechanisms, possibly to ensure nutrient supply needed to sustain an ongoing infection." (PMID 31936570, 2020). "Human cytomegalovirus (HCMV) relocalizes mTOR to the site of viral replication during infection of human foreskin fibroblasts (HFFs)/U373-MG cells (a human glioblastoma-astrocytoma cell line)." (PMID 31936570, 2020). "Further studies should investigate the importance of this finding in animal models of infection and further characterize the molecular and metabolic interactions between iron and mTOR and their importance for the control of infectious disease by the host." (PMID 31832425, 2019). "In the case of two persistently-infecting viruses, hepatitis B (HBV) and hepatitis C virus (HCV), it is known that they activate PI3K/Akt/mTOR signaling for cell survival and suppression of virus replication for long-term infection." (PMID 31601269, 2019). "To further determine the involvement of autophagy during JUNV infection, we investigated the effect of autophagosome induction using rapamycin (Rap), which induces autophagy by blocking the mTOR pathway." (PMID 31216340, 2019). "The signaling pathways involving mTOR and Akt play a crucial role in the glycolytic shift in macrophages during infection." (PMID 30930886, 2019). "Infection of the murine macrophage cell line RAW264.7 with Salmonella resulted in the induction of mTOR activity, anaerobic glycolysis and inhibition of the TCA activity as reflected by reduced pyruvate and increased lactate levels." (PMID 31832425, 2019). "A few persistently-infecting viruses activate the PI3K/Akt/mTOR pathway to maintain long-term infection." (PMID 31601269, 2019). "We did not observe any alterations in the phosphorylation of either the downstream targets of mTOR or AMPK after infection of AGS cells with H. pylori wild type or the isogenic Hp∆ggt mutant strain." (PMID 31185677, 2019). "Recent data provide evidence for metabolic re-programming of immune cells including macrophages during infection which is centrally controlled by mTOR." (PMID 31832425, 2019). "Macroautophagy is triggered by a stimulus, such as starvation, hypoxia, mammalian target of rapamycin (mTOR) inhibition, or infection." (PMID 31083536, 2019). "We herein studied the effects of iron perturbations on metabolic profiles in macrophages upon infection with the intracellular bacterium Salmonella enterica serovar Typhimurium and analysed for a link to the mTOR pathway." (PMID 31832425, 2019). "Infection with Mfa1-positive P. gingivalis strains induced expression of p-mTOR, p-ULK1 and Raptor, consistent with the conclusion that p-Akt activation blocks autophagy induction." (PMID 31608069, 2019). "Consistent with the increase in lipogenesis, the expression of the enzyme acetyl-CoA carboxylase (ACC), which catalyzes the rate-limiting step of fatty acid synthesis, is significantly elevated by 48 h post infection with HCMV in an mTOR-dependent manner." (PMID 30699959, 2019). "In the process of infection, the phosphorylation levels of mTOR and p70S6K were suppressed by CVB3 infection and repromoted by CPCs-Ex, but that change of 4EBP1 was on the contrary (P < 0.05)." (PMID 31534118, 2019). "PI3K/AKT/mTOR signaling was also altered upon infection, consistent with prior work that showed RVFV infection attenuates Akt and downstream mTORC1 activity." (PMID 31136639, 2019). "In summary, our data indicate that both, the mTOR pathway and iron perturbations have central regulatory effects on metabolic pathways in the course of infection of macrophages with the intracellular bacterium Salmonella enterica serovar Typhimurium (S. Tm)." (PMID 31832425, 2019). "The findings indicate the specific activation of the Ras/PI3K-Akt and mTOR signaling pathways during the cortical infection." (PMID 30522435, 2018).
infection (continued). "Despite the increasing number of investigations examining the effects of mTOR on the immune system, little emphasis has been placed on the function of this pathway in macrophages during infection." (PMID 29515594, 2018). "EDSV infection resulted in significant reductions in phosphorylation of p-pI3k, p-Akt, and p-mTOR in DEFs at indicated time points post-infection." (PMID 29896171, 2018). "In this study, we tested the therapeutic efficacy of several mTOR inhibitors in controlling infection with Leishmania major." (PMID 30133440, 2018). "After infection, cells were treated for 96 h with either 200 nM rapamycin, an mTOR inhibitor, or 100 nM bafilomycin, an indirect mTOR signaling inductor." (PMID 29396410, 2018). "In HeLa cells, HVJ-E infection triggered autophagy through the PI3K/Akt/mTOR/p70S6K pathway in an ERK1/2-dependent manner, and the induction of autophagy promoted apoptosis in an Atg3-dependent manner." (PMID 30534001, 2018). "Upon infection of human enterocytes by this bacterium, amino acid starvation occurs that, at a later stage of infection, stimulates recruitment of mTOR." (PMID 30234109, 2018). "Since targeting ULK complex formation or ATG complex, rather than affecting the upstream pathways, seems to have a specific and stronger impact on autophagy, mTOR has been the target of interest for promoting autophagy upon infection with Mycobacteria." (PMID 29441052, 2018). "SINV was also shown to exhibit efficient replication in HEK293 cells in the presence of Akt/mTOR inhibitors and even to suppress activation of the pathway at late stages of infection." (PMID 29495654, 2018). "PI3K-Akt-mTOR signaling pathway plays a vital role in regulating the infection course of many viruses." (PMID 28475412, 2018). "As expected, the levels of p-mTOR and p-S6K were dramatically increased after pH1N1 infection in MLE12 cells, whereas oseltamivir and rapamycin reduced mTOR activity synergistically." (PMID 30422993, 2018). "This is consistent with the observed localization of mTOR to a juxtanuclear region as early as 24 h following infection." (PMID 30042195, 2018). "It is plausible that curtailed or weak IL-2 signals drive lower levels of STAT-5, Akt and mTOR activity, thus resulting in lesser proliferation, effector differentiation and trafficking to peripheral sites of infection." (PMID 30619342, 2018). "Our data show that altered eIF4E/4E-BPs expression can act to promote HSV1-dICP0 infection under prolonged mTOR inhibition." (PMID 30138450, 2018). "The infection with Shigella, Salmonella, P. entomophila, and P. aeruginosa also reported to inhibit the level of expression of mTOR." (PMID 28932706, 2017). "Wt LysM, mTOR LysM and Rictor LysM mice received a primary subcutaneous infection and then 4 weeks later were given a secondary intravenous infection of 1000 L3 N." (PMID 28128208, 2017). "Viral protein levels were reduced and viral mRNA levels decreased to a lesser extent in the presence of Torin1 at 10 hours post-infection, indicating that mTOR activity is important for optimal influenza virus mRNA and protein production." (PMID 28953980, 2017). "The lung viral load on day 10 post-infection in mice that were administered sirolimus highlights the importance of immune competency and mTOR signaling in controlling lung viral load." (PMID 28693498, 2017). "The increased viral titers at day 10 indicates that mTOR signaling is critical during the adaptive immune phase of the infection that is responsible for clearance of the virus." (PMID 28693498, 2017). "We demonstrated that GRAIL expression during infection was modulated by the mammalian target of the rapamycin (mTOR) pathway, since addition of IL-2 or CTLA-4 blockade in splenocytes from mice 21 days post infection led to a reduction in GRAIL expression." (PMID 28114324, 2017).
infection (continued). "Other pathways involved in translational regulation such as regulation of eIF4 and p70S6K signaling and mTOR signaling, as well as protein ubiquitination and mitochondrial dysfunction were also induced at both times of infection in human cells." (PMID 28491823, 2017). "In the early phase of infection, Salmonella triggers acute intracellular amino acid starvation and mTOR inhibition, resulting in the induction of autophagy." (PMID 28783107, 2017). "The present study indicated that in 12 and 24 h of infection, the mTOR was downregulated during K. pneumoniae infection which clearly corroborated with earlier findings on deprived nutrient signals." (PMID 28932706, 2017). "So we examined the regulation of mTOR in host during infection with K. pneumoniae in 2D gel analysis." (PMID 28932706, 2017). "Yet as infection progresses, viral replication becomes increasingly resistant to mTOR inhibitors, even though these inhibitors continue to efficiently disrupt eIF4F complex formation." (PMID 27089357, 2016). "During infection, the metabolic checkpoint kinase Mechanistic Target of Rapamycin (MTOR) controlled lipogenesis through the Serum Response Element Binding Protein 1 and 2 (SREBP1/2) transcription factors." (PMID 27942021, 2016). "As suggested by the authors, a potential explanation of this paradox is likely that HCV infection is inducing autophagy for establishment of infection, while activating mTOR signaling for hepatocyte growth." (PMID 27231932, 2016). "Upon the infection of Ad5-AlncRNA, the phosphorylation of mTOR, GSK3β, S6K and 4EBP1 was reduced, sequentially p27 expression was increased while cyclin D1 expression was reduced." (PMID 27689326, 2016). "TGF-β suppressed mTOR activation in T cells early during infection, which promoted Tfh cell differentiation by limiting IL-2 signaling." (PMID 27242787, 2016). "We adopted a hybrid strategy in our patient based on the efficacy of immunosuppression with mTOR inhibitors on outcome in terms of eradicating GCV-resistant infection of recent studies and on the latest guidelines recommending foscarnet administration." (PMID 26942027, 2016). "At 72 h after infection, the activations of phosphorylated mTOR showed approximately 2.7-fold increases versus those in the 0 h cells." (PMID 27330868, 2016). "This early event leads to the repression of mTOR at the mid-stage of infection; we also have evidence of a concurrent activation of the PERK pathway by ATM kinase." (PMID 26938301, 2016). "Autophagy in human tissues is induced through the inhibition of the mammalian target of rapamycin (mTOR) under various conditions, e.g., starvation or infection of cells." (PMID 27973418, 2016). "In fact HCMV paradoxically requires increased activation of both AMPK and mTOR during infection for efficient replication." (PMID 27089357, 2016). "The cellular stress imposed by an acute infection requires that the virus commandeer mTOR signaling to sustain protein synthesis, which is the case for WNV, SINV and VSV." (PMID 27231932, 2016). "When added at the time of infection, mTOR inhibitors limit viral DNA accumulation and thus the transcription of HCMV late genes." (PMID 27089357, 2016). "Infection with CSFV Shimen led to progressive accumulation of p-mTOR signals over time, and the maximal induction was found at 72 h postinfection." (PMID 27330868, 2016). "Similar reactivation of MTOR by Salmonella suppresses autophagy induced by a host amino acids starvation response during infection of epithelial cells." (PMID 27942021, 2016). "Activation of mTOR during infection depended on IQGAP1, since S6K phosphorylation remained at baseline in IQGAP1-/- MEFs." (PMID 26473364, 2015). "CA16 infection inhibited Akt/mTOR signaling and activated extracellular signal-regulated kinase (ERK) signaling, both of which are necessary for autophagy induction." (PMID 25853521, 2015).
infection (continued). "TGF-β suppressed the expression of the high affinity IL-2Rα chain CD25, which restricted IL-2 signaling via STAT5 and mTOR in Tfh progenitor cells early during infection in vivo." (PMID 25569154, 2015). "The results suggested a putative MTOR phosphorylation-dependent counteracting mechanism in the early infection phase and indicated that intracellular amastigotes were cleared by autophagy in BMDM in the late infection phase." (PMID 26226952, 2015). "During early infection by L. (L. ) major, Jaramillo and peers reported that the glycoprotein gp63 induces mTOR cleavage and inhibits the formation of the mTORC1 complex." (PMID 26052705, 2015). "At 1 hr of infection of IQGAP1+/+ MEFs, WT or ospB complemented S. flexneri induced more phosphorylation of S6K than the ospB mutant, indicating that OspB delivered by S. flexneri activates mTOR early during infection." (PMID 26473364, 2015). "In this study, we demonstrate that the Shigella type 3 secreted effector protein OspB activates mTOR activity during cellular infection." (PMID 26473364, 2015). "Assuming that this mechanism is shared by L. (V. ) braziliensis and that its effects in mTOR signaling prevail at later infection times, it is possible that in the context of our work, gp63 down-regulates mTOR reducing Lipin1 phosphorylation." (PMID 26052705, 2015). "In contrast, hyperphosphorylation of MTOR was detected after infection with promastigotes, and there was a decreased infection rate after knocking down p-MTOR with RNA interference." (PMID 26226952, 2015). "This is consistent with our previous studies indicating that mycobacteria induce mTOR independent autophagy during infection." (PMID 24528777, 2014). "We then review the known functions mTOR serves in regulating T cell trafficking under homeostasis and upon infection." (PMID 25653651, 2014). "A recent study proposed that infection of macrophages with virulent L. pneumophila strains (both Dot+ and Δ5) leads to downregulation of mTOR activity, which is sufficient to suppress cap-dependent protein translation initiation." (PMID 25058342, 2014). "We analyzed the hepatic expression of phospho-mTOR by Western blot at different RHDV-infection periods." (PMID 24490870, 2014). "Phosphorylation of mTOR also augmented in early periods of infection and there was an increase in the expression of the endoplasmic reticulum chaperones BiP/GRP78, CHOP and GRP94." (PMID 24490870, 2014). "Kaech and colleagues recently demonstrated that Akt and mTOR signaling are impaired in CD8+ effector T cells following a chronic viral infection as compared to an acute infection." (PMID 25653651, 2014). "Infection of cells with various pathogens and mTOR inhibition via Rapamycin or nutrient starvation leads to the isolation of pathogens within autophagosomes via mTOR dependent autophagy." (PMID 24528777, 2014). "If these LVAD patients, often with specific risks such as concomitant infection, receive Thymoglobulin induction plus early introduction of a mTOR inhibitor, the intensity of immunosuppression can become supratherapeutic." (PMID 24382994, 2013). "The risk of adverse events, such as oedema, proteinuria and hyperlipidaemia, was higher for mTOR inhibitors, but infection rates were similar." (PMID 24565283, 2013). "There is, however, accumulating evidence that the avoidance of CNIs and the use of mTOR inhibitors also confer benefits with respect to the development of malignancy and also some post-transplant infections." (PMID 24565283, 2013). "Several recent studies have identified the host AMP-activated protein kinase (AMPK) and mammalian target of rapamycin (mTOR) kinases as two important regulators of cellular metabolism whose activities are often altered during infection." (PMID 24098109, 2013).